AQP4 (aquaporin 4)
Diseases named in the same sentence as AQP4 in open-access papers (continued):
Sharing a sentence is not in itself a finding about the gene and the disease.
infection (continued). "The mean lectin and AQP4 intensity profiles for the hippocampus showed an upregulation of AQP4 following initial infection at 13-months old, which was no longer present at 18-months old (Fig. 3Bii)." (PMID 40051735, 2025). "By investigating AQP4 as a marker of astrocyte endfeet, which are an active component of BBB, we show an increased astrocytic endfeet coverage of cerebral capillaries in the hippocampus following infection." (PMID 37496672, 2023). "Of interest, although HuNoV infection induced the expression of AQP4 in HIEs (data not showed), AQP4 expression was not affected in Caco2 cells transfected with full-length HuNoV cDNA." (PMID 35458572, 2022). "During the first 3 weeks post-infection the percentage of Th2 cells increased slowly in both AQP4 KO and WT mice and there was no apparent difference in Th2 responses between these two groups." (PMID 25604731, 2015). "Subsequent resolution of the infection and tissue damage limits AQP4 exposure at non-CNS draining lymph nodes and prevents the activation of AQP4-specific autoimmune effector cells." (PMID 18510734, 2008). "Are recurrent or specific infections near the neck and head where the draining cervical lymph nodes have a higher concentration of AQP4 protein more likely to be the priming event for ON or LETM?" (PMID 18510734, 2008). "Strikingly, we observed abundant infection in astrocytes, as indicated by the presence of viral N protein, S RNA, and dsRNA, with 90% of infected cells expressing glial fibrillary acidic protein (GFAP) or Aquaporin 4 (AQP4) throughout the outer subventricular zone (SVZ) of primary cortical tissue." (PMID 35858406, 2022). "Moreover, attacks are preceded by acute infection in 20-30 % of cases of AQP4-IgG-positive NMO, suggesting that infection-related immunologic changes or infection-related BBB disruption may trigger disease activity." (PMID 27802825, 2016). "In the syndrome hypothesis above, it is likely that AQP4-specific B cells are readily induced in certain infections but NMO does not result, or is self-limiting as is typical for pediatric NMO patients." (PMID 18510734, 2008). "The two patients in this study developed the condition following infection, and tests for NMDAR, CASPR2, LGI1, AMPA, GABA, DPPX, mGluR, GAD65, MOG, GFAP, and AQP4 antibodies were all negative." (PMID 38765268, 2024). "Moreover, the fact that antibodies to HTLV-1 were absent in all patients with NMOSD suggests that HTLV-1 is not a common trigger of acute attacks in patients with AQP4-Ab positive NMOSD, a disorder in which relapses are often preceded by infection, in populations with high HTLV-1 seroprevalence." (PMID 22808032, 2012).
inflammatory disease of the central nervous system (21 papers, 2018 to 2026). "Changes in AQP4 activity and expression have been implicated in several central nervous system disorders." (PMID 36688175, 2022). "Demyelinating diseases of the central nervous system associated withautoantibodies against aquaporin-4 and myelin-oligodendrocyte-glycoproteinare mediated by different immunopathological mechanisms compared to multiplesclerosis." (PMID 31205739, 2019). "PVS and AQP4 are two crucial structures involved in the glymphatic system with implications for various central nervous system diseases." (PMID 39144708, 2024). "NMO and NMOSD are autoimmune-mediated central nervous system disorders distinguished by the presence of serum aquaporine-4 IgG antibody (AQP4-Ab)." (PMID 38732279, 2024). "Regarding diseases of the central nervous system, anti-aquaporin 4 (AQP4) antibodies were found to be positive in patients with neuromyelitic optica." (PMID 33917929, 2021). "It has been reported that any central nervous system disease characterized by upregulation of AQP4 on astrocytes may also involve the AQP4/TGFB1 pathway." (PMID 38383423, 2024).
connective tissue disease (17 papers, 2016 to 2025). "We report a 57-year-old female patient who met the diagnostic criteria for aquaporin 4 (AQP4)-IgG positive NMOSD with undifferentiated connective tissue disease and multiple peripheral neuropathy." (PMID 37173637, 2023). "Comorbidity of connective tissue disease, Hcy levels, and 24h IgG synthesis rate may be independent risk factors for AQP4-IgG positive highly active NMOSD." (PMID 34512539, 2021). "In conclusion, we demonstrated that connective tissue disease comorbidity, Hcy levels, and 24h IgG synthesis rate may be independent risk factors in patients with AQP4-IgG positive highly active NMOSD." (PMID 34512539, 2021). "Upon comparing MOG-ON and AQP4-ON patients, significant differences were observed regarding connective tissue diseases (CTDs) and related antibodies." (PMID 38988608, 2024). "In contrast, AQP4-ON patients frequently showed comorbid connective tissue diseases (30.0% vs. 0%, p = 0.004) and antinuclear antibody abnormalities (40.0% vs. 7.7%, p = 0.012)." (PMID 38988608, 2024). "Herein, we report one case of AQP4-positive NMOSD coexisting with undifferentiated connective tissue disease and peripheral neuropathy." (PMID 37173637, 2023). "Connective tissue disorders (CTD), for example, which relatively frequently co-exist with AQP4-IgG-positive NMOSD, are associated with OCB in neurological patients in about 25-30% of cases." (PMID 32883348, 2020). "Fourth, sera with autoantibodies associated with connective tissue disease are known to be particularly ‘sticky’ in the FACS assay, and can cause false-positive results by non-AQP-4 Ab-specific binding." (PMID 27658059, 2016). "Serum anti-AQP-4/anti-MOG and antibodies panel for connective tissue diseases were still unremarkable." (PMID 36530641, 2022). "Serum antibodies panel for infectious diseases (including HIV, Herpesviruses, and Borrelia) was unremarkable as well as anti-AQP-4/MOG and connective tissue diseases antibodies." (PMID 36530641, 2022). "Serum anti-AQP-4/anti-MOG antibodies resulted negative as well as connective tissue diseases panel except for the positivity of anti-nuclear antibodies (titer 1:160), considered a non-specific finding." (PMID 36530641, 2022). "Serum anti-AQP-4 and anti-MOG antibodies were negative, as well as an antibody panel for connective tissue diseases." (PMID 36530641, 2022). "Anti-AQP-4/anti-MOG and antibodies for connective tissue diseases were negative." (PMID 36530641, 2022).
brain diseases (14 papers, 2017 to 2025). "Although AQP4 has been implicated in a wide range of brain disorders, its involvement in FXTAS remains unclear." (PMID 36688175, 2022). "It was also reported that AQP4 is associated with neuroinflammation in brain diseases." (PMID 29599893, 2018). "Recently, AQP4 has been reported to play important roles in brain edema formation at the early stage of several brain diseases, and thereby participates in the secondary neuronal damage and brain dysfunction at the later stage." (PMID 35177771, 2022). "Although indirectly, genome-wide linkage studies have repeatedly pointed out the role of AQP4 in the development of brain disorders." (PMID 36688175, 2022). "We hypothesize that AQP4 could be a target for the prevention and treatment of certain brain diseases through the regulation on the glymphatic system." (PMID 40012567, 2025). "We hypothesize that AQP4 could therefore be a target for preventing and treating certain brain diseases." (PMID 40012567, 2025). "AQP4-ko mice could be useful for clarifying the role of AQP4 in brain water dynamics and for developing new treatments for brain diseases that target AQP4." (PMID 36685250, 2022). "Although the detailed molecular mechanism of brain water transport is lacking, AQP4 was implicated as a key determinant in the lymphatic system and, therefore, a potential therapeutic target for brain disorders presenting edema." (PMID 35682594, 2022).
retinopathy (9 papers, 2016 to 2025). "Since they express AQP4 water channel proteins, they might be a direct target of AQP4-ab and a potential cause of a primary retinopathy in NMOSD." (PMID 29515685, 2018). "The study suggested that AQP4 upregulation in diabetes is compensatory, and its downregulation exacerbates retinopathy." (PMID 41155961, 2025). "AQP4-IgG-seropositive NMOSD is an astrocytopathy, and a primary retinopathy caused by antibody-mediated damage is supported by animal studies and recently also clinical studies." (PMID 31345223, 2019). "AQP4 knockdown worsened retinopathy, increasing retinal permeability, thickness, and inflammation." (PMID 41155961, 2025). "The significance of this finding is that AQP4, which is detected primarily in the blood vessels, astrocytes, and Müller cells, is involved in water flux from the blood vessels to the retina and retinal swelling, a major characteristic of retinopathy." (PMID 32024231, 2020). "Furthermore, the presence of a primary retinopathy in AQP4‐IgG‐seropositive NMOSD, mediated by AQP4‐IgG, could be a pathophysiologic explanation for the observed changes." (PMID 33784027, 2021).
inflammation (8 papers, 2012 to 2023). Aberrant reaction of the microcirculation characterized by movement of fluid and leukocytes from the blood into extravascular tissues. "The decreased expression of AQP4 was associated with the induction of allergic or infection-related diarrhea and intestinal inflammation." (PMID 36771343, 2023). "Interestingly, AQP4 is also linked to intraocular inflammation, as AQP4 and Kir4.1, the two main channel proteins in retinal Müller glia cells are differentially regulated during ocular inflammation." (PMID 23236410, 2012). "The results support the effects of ISOF via the cAMP/AQP4/SPP1/PIK3C3 axis on chronic airway inflammation, demonstrate its potential to reduce Th17 differentiation and thus the Th17/Treg balance, and provide potential targets for the treatment of this disease." (PMID 37817209, 2023). "Liquiritigenin (Rt: 3.034), is reported to ameliorate renal inflammation through suppression of AQP4/NF-kB/IkBa signaling as well as NLRP3 inflammasome in hyperuricemic rats, thus showing anthyperuricemic effects." (PMID 36474572, 2022).
psychiatric disorder (7 papers, 2020 to 2025). A disorder characterized by behavioral and/or psychological abnormalities, often accompanied by physical symptoms. "The properties of water channels, particularly AQP4, are of significant interest in psychiatric disorders due to the abundance of AQP4 tetramers at the blood-brain interface." (PMID 40717781, 2025). "Found primarily at the end-feet of astrocytes, the aquaporin 4 (AQP4) gene has been suspected to play putative roles in the development of psychiatric disorders as well as the clearance of the glymphatic system." (PMID 32676041, 2020). "Hence, our study confirms the role of AQP-4 as a key component of the glymphatic system and its potential role as a marker of glymphatic impairment, also in the context of psychiatric disorders." (PMID 39234773, 2024). "Polymorphisms of the AQP4 gene have not been studied intensively in psychiatric diseases, possibly because of the highly conserved nature of the coding region." (PMID 32676041, 2020). "In this study, cerebrospinal fluid (CSF) concentration of AQP4, amyloid-β, total tau and P-tau were determined in 103 CSF samples from patients affected by neurodegenerative dementias (AD and FTD) or psychiatric diseases and 21 controls." (PMID 36115967, 2022).
infectious disease (5 papers, 2018 to 2025). A disorder directly resulting from the presence and activity of a microbial, viral, or parasitic agent in humans. "Given that many women with seropositive NMO are of childbearing age, IVIg may be useful as rescue therapy in AQP4-IgG-positive NMO attacks refractory to IVMP in pregnant patients, especially when complicated with infectious diseases." (PMID 29552355, 2018).
metabolic disease (4 papers, 2023 to 2026). A congenital disorder (due to inherited enzyme abnormality) or acquired (due to failure of a metabolically important organ) disorder resulting from an abnormal metabolic process. "Hence, metabolic diseases, such as hypertension, diabetes, and dyslipidemia, can cause AQP4 depolarization, further resulting in dysfunction of the glymphatic system and triggering the development of AD." (PMID 38270115, 2024).
myopathy (4 papers, 2011 to 2022). A disease of the muscle in which the muscle fibers do not function properly. "Several studies have reported that AQP4 is markedly decreased in muscle fibers from myopathies in which DGC protein expression is severely compromised, such as DMD and LGMDs." (PMID 21552523, 2011). "In addition, aquaporin-4 (AQP-4) expression is detected in the muscle fibers of a patient with GNE myopathy, especially at the RVs or their surrounding areas." (PMID 35904705, 2022).
renal disease (4 papers, 2017 to 2025). "Similar to AQP4, AQP2 not only influences fluid transport in many epithelial and endothelial tissues, but also participates in the regulation of inflammation and apoptosis in renal diseases." (PMID 35386692, 2022). "Though renal disease has not been reported in NMO, perhaps some patients manifest a mild urinary concentrating defect, as found in AQP4 knockout mice, and perhaps urinalysis might reveal cellular evidence of collecting duct injury." (PMID 28750658, 2017).
bacterial infection (3 papers, 2010 to 2020). "neutrophilic pleocytosis and elevated l-lactate CSF concentrations render the condition—just like AQP4-IgG-positive NMOSD—a relevant differential laboratory diagnosis of (especially nonpurulent or chronic) bacterial infection in a subset of patients." (PMID 32883348, 2020).
cerebral artery (3 papers, 2014 to 2021). "In another study, immunohistochemical staining showed that AQP4 levels were nearly abolished at the ischemic core after 2 hours of middle cerebral artery occlusion and 4 hours of reperfusion, even though the total amount of AQP4 determined by Western blot was unchanged." (PMID 26526878, 2015). "We showed that calmodulin kinase (CaM) directly binds to AQP4 and that this binding is inhibited by TFP, suggesting a direct role of TFP in lowering spinal cord oedema." (PMID 34685662, 2021).
CNS neoplasms (3 papers, 2021 to 2024). "This investigation systematically investigated the oncogenic role of AQP4 across 33 CNS tumors found in GEO and TCGA datasets." (PMID 34113257, 2021). "This study contributes toward current knowledge regarding the role of AQP4 in CNS tumors." (PMID 34113257, 2021).
immune diseases (3 papers, 2012 to 2024). "The results showed that both groups had gender ratio, abnormal brain MR1 expression, serum AQP4-IgG-positive, and other immune diseases and symptoms." (PMID 35360267, 2022). "There were significant differences in gender ratio, abnormal expression of brain MR1, positive serum AQP4-IgG, and other immune diseases and symptoms between the two groups (P < 0.05)." (PMID 35360267, 2022).
movement disorder (2 papers, 2024). Neurological conditions resulting in abnormal voluntary or involuntary movement, which may impact the speed, fluency, quality and ease of movement. "Amongst these four diseases, LETM and AQP4-IgG are independent risk factors for spinal movement disorders, while MOG-IgG and African American race are associated with a lower risk." (PMID 38977461, 2024). "Movement disorders were present in 73% of the total patients and were most frequent in NMOSD with AQP4-IgG (92%) and least frequent in MOGAD (57%)." (PMID 38977461, 2024). "Movement disorders were compared among patients with NMOSD with and without AQP4-IgG, MOGAD, and ITM." (PMID 38977461, 2024).
respiratory disease (2 papers, 2011 to 2023). "A subset of genes co-expressed with AQP4 and associated to respiratory disease were assigned to potential anti-tumorigenic function like CAV1, EDNRB, or SELENBP1, whereas genes more related to pro-tumorigenic function like CDK2, FOXM1, PLK1 or RRM1 were found to be anti-correlated with AQP4." (PMID 21548930, 2011). "Meanwhile, there have been first reports of the anti-inflammatory effects of AQP4 and PIK3C3 in respiratory diseases." (PMID 37817209, 2023).
hepatobiliary disorder (1 paper, 2025). A non-neoplastic or neoplastic disorder that affects the liver, bile ducts, and gallbladder. "Additionally, AQPs have been associated with various hepatobiliary disorders, and AQP1 and AQP4 are involved in mechanisms of reabsorption/secretion of water, but there was only a significant increase in AQP3 levels in liver tissue." (PMID 41010898, 2025).
peripheral neuropathy (1 paper, 2013). A disorder affecting the peripheral nervous system. "Undetermined humoral factors other than anti-AQP-4 autoantibody were suggested to cause peripheral neuropathy in NMO." (PMID 24308009, 2013). "Moreover, anti-AQP-4 antibody cannot cause peripheral neuropathy because AQP-4 is a cell membrane water channel, that is, expressed at the astrocyte foot processes, and there are no astrocytes in the PNS." (PMID 24308009, 2013). "Because anti-AQP-4 antibody was discovered in the serum of NMO patients as a favorable diagnostic marker, autoantibodies might be associated with peripheral neuropathy in NMO patients." (PMID 24308009, 2013).
AQP4 also shares sentences with these, for which no sentence is quoted: obstructive hydrocephalus (15 papers); cerebral oedema (11); central nervous system demyelinating disease (6); adenocarcinoma (5); narcolepsy (5); cerebellar degeneration (3); cognitive disorder (3); communicating hydrocephalus (3); ischemia reperfusion injury (3); pilocytic astrocytoma (3); pneumonia (3); AIDS (2); aneurysm (2); antiphospholipid syndrome (2); atherosclerosis (2); atrophic gastritis (2); atypical hemolytic-uremic syndrome (2); autoimmune optic neuritis (2); cardiovascular disease (2); celiac disease (2); cerebral artery occlusion (2); diabetic neuropathy (2); endocrinopathies (2); Guillain-Barre syndrome (2); hepatocellular carcinoma (2); herpes zoster (2); hippocampal atrophy (2); hyperhomocysteinemia (2); hyperlipidemia (2); hyperopia (2).
A further 153 diseases each share a sentence with AQP4 in 2 papers or fewer.